IDH1 (isocitrate dehydrogenase (NADP(+)) 1)
Diseases named in the same sentence as IDH1 in open-access papers (continued):
Sharing a sentence is not in itself a finding about the gene and the disease.
glioblastoma (continued). "The maximum TBF in the group of IDH1-mutant glioblastomas was 95.35 ± 74.96 mL/100 g/min, the normalized blood flow was 4.95 ± 3.53." (PMID 35741254, 2022). "Therefore, the effects of Cyn were assessed on two patient-derived glioblastoma cell lines, NULU and ZAR, genetically characterized by IDH1/2 wild-type and unmethylated MGMT gene promoter, thus by a TMZ-resistant phenotype." (PMID 35884887, 2022). "Conversely, recently it has been shown that the median overall survival from the first progression was not significantly different between the IDH1 mutant and wild-type group when primary and secondary glioblastomas were combined." (PMID 35996504, 2021). "A biopsy through a laminectomy Th9 was performed and revealed a Glioblastoma WHO IV (IDH-1 wild type, no MGMT methylation)." (PMID 33094355, 2021). "In addition, in the third cIMPACT-NOW report, the committee recommended reclassifying IDH1/2 wild-type diffuse lower-grade gliomas of WHO grade II and III (LGG) as diffuse astrocytic glioma, IDH1/2-wt with molecular features of glioblastoma." (PMID 34307160, 2021). "MET SUVmax and T/N ratio did not allow differentiation between IDH1-mutant and IDH1-wildtype in diffuse astrocytoma and anaplastic astrocytoma or IDH1-wildtype diffuse astrocytoma and anaplastic astrocytoma and glioblastoma." (PMID 34743250, 2021). "Several mutations in TCA Cycle enzymes and enzymes in adjacent metabolic pathways are commonly found in glioblastomas, and none more prevalently than isocitrate dehydrogenase 1 (IDH1) and 2 (IDH2)." (PMID 34277624, 2021). "Owing to their relatively favorable prognosis compared to IDH1-wt glioblastomas, IDH1-mut glioblastomas and LGGs have not been extensively investigated." (PMID 32120790, 2020). "With the recent evidence that non-enhancing WHO grade II and III astrocytomas lacking the IDH1 mutation should be classified as glioblastoma (GBM) and that not all high-grade gliomas enhance, there is a need to investigate other imaging technologies to better assess tumour burden." (PMID 33182433, 2020). "BCAT1 expression could be suppressed by ectopic overexpression of mutant IDH1 in immortalized human astrocytes and suppression of BCAT1 significantly reduce tumor growth in a glioblastoma xenograft model." (PMID 33072547, 2020). "In glioblastomas, WT1 significantly associated poor prognostic variables: older age, negative-IDH1 status, high Bcl2 and Ki67 labelling indices (p=0.04, <0.001, =0.001 and <0.001 respectively)." (PMID 32856872, 2020). "Glioblastoma is a WHO grade IV disease with poor prognosis, and only about 10% of these malignancies possess IDH1/2 mutation without 1p19q co-deletion." (PMID 32120790, 2020). "Using the defined surrogate markers, we categorized an additional 202 in-house IDH1-wt glioblastomas into E&F-dependent or -independent samples that were not included in the screening set." (PMID 32120790, 2020). "EGFRvIII expression was found in 4 of 19 (21%) of IDHwt glioblastomas and not in p.IDH1-R132H cancers, confirming results in the test cohort." (PMID 31747973, 2019). "Following gross-total resection, the histopathological diagnosis was that of glioblastoma versus anaplastic PXA, and the tumor had high-grade morphological features, a BRAF V600E mutation, and was IDH1 (R132H) negative." (PMID 31806041, 2019).
glioblastoma (continued). "Indeed, molecular alterations in various genes such as EGFRvIII, IDH1 and PTEN have been found in glioblastoma-derived EVs." (PMID 31284524, 2019). "The following patients were included: seven with LGG (four diffuse, isocitrate dehydrogenase 1 (IDH1) R132H mutant astrocytomas; three IDH1 R132H mutant, 1p19q co-deleted oligodendrogliomas) and seven with HGG (six IDH wild-type glioblastomas; one IDH wild-type astrocytoma)." (PMID 30888488, 2019). "Grade II astrocytomas contain several IDH1-R132H –positive cells, while grade IV tumors, glioblastomas, are mostly negative for IDH1-R132H –immunostaining." (PMID 29914429, 2018). "Isocitrate dehydrogenase (IDH1) negative glioblastoma patients with baseline pSMAD2+ in cytoplasm had median overall survival (OS) 9.5 months vs. 6.9 months for patients with no tumor pSMAD2 expression (p = 0.4574)." (PMID 28481241, 2017). "As a result, to be able to reliably classify diffuse gliomas, both analyses (ATRX, IDH) should be performed in these tumors, in case they are not already classified as immunohistochemically IDH1 R132H-negative primary glioblastomas." (PMID 27311324, 2016). "The tumor cells were all derived from IDH1-negative tumors suggesting that they were primary glioblastomas." (PMID 27454178, 2016). "Moreover, a recent investigation (in which a molecular registry of 274 glioblastoma patients was used) showed that the poorest OS and PFS were observed in wild-type IDH1 glioblastomas with an unmethylated MGMT promoter." (PMID 27834917, 2016). "Of these, two patients with IDH1-R132H negative tumours demonstrated ring-enhancing lesions on their pre-operative MRI; a pattern more consistent with a glioblastoma." (PMID 25849605, 2015). "Consistent with previously published results, short-term (5 passages) expression of IDH1-R132H in the human U87MG glioblastoma line or the murine Ink4a-Arf−/− astrocytic line did not significantly alter the epigenetic landscape." (PMID 26503470, 2015). "Although mutations in these genes have been reported in other cancer types such as glioblastoma and mesothelioma, BAP1, IDH1 and IDH2 have not been previously linked to HCC." (PMID 25159915, 2014). "The epigenomic alterations produced by a mutant IDH1 activate gene expression programs resembling proneural glioblastomas but not other glioblastomas." (PMID 24202337, 2013). "In support of this, reduction in TET2 enzyme levels by promoter methylation has recently been reported in low grade diffuse gliomas lacking IDH1/2 mutations, and loss of the TET2 locus (4q24) has been reported in approximately 2% of glioblastomas." (PMID 22829908, 2012). "Fourteen (11.6%) had IDH1-mutant WHO grade 3 or 4 astrocytomas, and 107 (88.4%) had IDH1 wild-type glioblastomas (IDHwt GBM)." (PMID 40261557, 2025). "For example, IDH1 immunostaining and 1p/19q FISH may suffice for classic oligodendroglioma, but methylation profiling helps resolve contradictory findings or uncover unexpected entities such as ependymoma profiles in presumed glioblastoma." (PMID 41487568, 2025). "Glioblastomas displayed negative IDH1 and retained ATRX in all seven cases." (PMID 39192927, 2024). "Given the “glioblastoma IDH-wild-type” is defined by what it is lacking (i.e., lack of IDH1 and IDH2 hotspot mutations) rather than what it is harboring, many opportunities exist to identify new CNS tumor entities with unique genetic and epigenetic features within this HGG group." (PMID 39335555, 2024). "In addition, HIF1α is involved in the regulation of miR-210-3p, CXCR7, CXCR4, IDH1, C-Met, SF/HGF, the S100A4/NMIIA axis, NO, VEGF, BAG3, and TDO2, and influences various aspects of the glioblastoma biology such as angiogenesis, invasion, metabolism, and therapy resistance." (PMID 38893207, 2024).
glioblastoma (continued). "In our cohort, after correcting for sex, age, and IDH1 mutation status, PFS in dexamethasone-naive glioblastoma patients correlated with double negative T cells, whereas patients treated with dexamethasone showed a correlation between PFS and regulatory T cells." (PMID 38318180, 2024). "Glioblastoma (GBM) is defined as a grade IV, isocitrate dehydrogenase 1/2 gene (IDH1/2) wild type astrocytic glioma with no mutations in histone H3 genes and is characterized by microvascular proliferation, necrosis and/or specific prognostic molecular features." (PMID 37162667, 2023). "As for glioblastoma with IDH1-wt, the resection of NCE tumor seems not to improve the prognosis." (PMID 37029174, 2023). "Well-known somatic drivers of glioblastoma (GBM) heterogeneity, including PDGFRA, IDH1, EGFR, and NF1, have altered how we treat patients, diagnose disease, and design clinical trials." (PMID 37252795, 2023). "Recently, it has been shown that wild-type IDH1 is highly expressed in a variety of cancer types, including non-small cell lung carcinoma (NSCLC), primary glioblastomas (GBM), and several hematological malignancies and is correlated with disease progression." (PMID 35743098, 2022). "This alteration, usually at arginine 132 (IDH1-R132H), is highly frequent in diffuse low-grade gliomas (LGGs; WHO grade II), in anaplastic astrocytomas (WHO grade III), and also in a smaller proportion of HGG originated from LGGs (secondary glioblastomas; WHO grade IV)." (PMID 34168976, 2021). "However, LANCL2 or EGFR amplification, and their co-amplification had no significant impact on OS in older (≥ 60 years) or IDH1/2-wild-type glioblastoma patients." (PMID 34461927, 2021). "Glioblastoma SF188 cells also produce 2HG at hypoxia, again despite lacking the IDH1/2 mutations." (PMID 31847543, 2020). "If current recommendations for the adult setting were to be applied, the presence of TERT promoter mutation in combination with an absence of IDH1/IDH2 mutation would be compatible with a diagnosis of diffuse astrocytic glioma, with molecular features of glioblastoma, WHO grade IV." (PMID 32493417, 2020). "Following 48 h of incubation with two different doses of anticonvulsants, significant effects could only be found in the expression of BCAT1, EAAT2 and GLUL in glioblastoma cells, whereas no changes in IDH1 and SLC7A11 expression were found." (PMID 30716120, 2019). "Additionally, no gliosarcoma samples carried IDH1/2 gene mutations, placing gliosarcomas among an IDH wild-type subtype of glioblastoma." (PMID 30818875, 2019). "Here, we determined the prognostic value of FZD7 for the overall survival of glioblastoma (GBM) patients, both as individual marker and taken in combination with the previously-described markers MGMT and IDH1." (PMID 27409829, 2016). "On the contrary, IDH1-negative tumours may represent an 'early' glioblastoma or, indeed, a bona fide glioblastoma which has been under-sampled." (PMID 25849605, 2015). "Thus glioblastoma cells generally appear to have a lower PC flux than the normal brain, but, as indicated in our study, mutant IDH1 cells have a higher PC flux that wild-type IDH1 cells." (PMID 25243911, 2014). "However, the wild-type IDH1/2 contradicts compatibility with a high-grade astrocytoma or oligodendroglioma, and the absence of TERT mutation and EGFR amplification does not align well with glioblastoma." (PMID 41323387, 2025). "Leveraging the high sensitivity of 18F-DOPA PET imaging for glioblastoma, the selected radiomics features, especially TBRmax, from pre-RT images can effectively stratify the patient cohort with un-methylated MGMT and wild-type IDH1, identifying the patients who may benefit most from DERT." (PMID 40881875, 2025).
glioblastoma (continued). "GBM, also known as glioblastoma, IDH-wildtype, is a diffuse astrocytic glioma with no mutation in the isocitrate dehydrogenase 1 (IDH1) or IDH2 genes." (PMID 39599889, 2024). "Here, we selected lung and glioblastoma cell lines without described mutation in IDH to investigate if treatment with a more specific 3rd generation small molecule SLC25A1 inhibitor CTPI2 would induce D-2-HG accumulation and mimic the HR-ness phenotype of IDH1/2 deficient cells." (PMID 35869047, 2022). "Two further enzymes that could be connected to changing hypotaurine levels were either not part of our RNA data set (glutamate decarboxylase like 1 [GADL1]) or only slightly increased in the IDH1-mut but not in IDH1-WT glioblastoma group (cysteine sulfinic acid decarboxylase [CSAD])." (PMID 34941573, 2022). "The RIGs included glioblastoma (GBM) with IDH1/2 wild type (n = 7), GBM not otherwise specified (n = 2), anaplastic astrocytoma with IDH1/2 wild type (n = 1), and anaplastic astrocytoma not otherwise specified (n = 1)." (PMID 35505351, 2022). "The early presentation of IDH1 mutation and CIMP that we have seen in our study suggests this is an early and important event in gliomagenesis and that if not acquired at an early stage is not gained during progression as no later stage glioblastoma presented with CIMP where the precursor did not." (PMID 25012071, 2014). "Our data are in line with previous research demonstrating overexpression of wild-type IDH1, but not IDH2, in glioblastoma." (PMID 41034696, 2025). "Approximately 83% of primary glioblastomas were ATRX positive, respectively, and all IDH-1 mutant cases were ATRX negative." (PMID 38003967, 2023). "The global gene profiling and protein-based classification of primary glioblastoma cell cultures revealed that WG4 and WG14 could be classified into the PN subtype; however, exome sequencing of the WG4 cells did not detect any mutation in IDH1 (data not shown)." (PMID 36900355, 2023). "IDH1-wt GSCs showed higher growth indices in NBE than IDH1-mut GSCs, but not all GSCs from IDH1-wt glioblastomas were dependent on E&F for cell growth." (PMID 32120790, 2020). "The concept behind it is the relationship between thrombosis and necrosis, which is stronger in glioblastoma IDH-wildtype, perhaps due to the intrinsic antithrombotic activity of mutant IDH-1; however, there is not enough evidence to support its widespread use for diagnosis." (PMID 39518074, 2024). "For example, tumor-induced edema could be used to predict the survival outcomes of glioblastoma patients based on MGMT promoter methylation, not the IDH-1 status." (PMID 37754483, 2023). "Furthermore, IDH1 is overexpressed in approximately 65% of primary glioblastomas (GBM), in the absence of IDH1 gene copy number gains or epigenetic activation." (PMID 31010244, 2019). "Glioblastomas displaying high LTB4 expression and IDH1 wild-type have a negative prognosis." (PMID 30279357, 2018).
astrocytomas (492 papers, 2011 to 2026). "Whereas clusters 1–8 captured IDH1/2-mutant astrocytomas of all grades, cluster 9 consisted of grade 4 IDH1/2-mutant astrocytomas with high mutational burden." (PMID 39584448, 2025). "Our results indicate that NMDA receptor and IDH1 gene mutations are significantly associated with patients with astrocytomas presenting with seizures." (PMID 40718831, 2025). "On the other hand, IDH1 mutations, a key molecular feature of astrocytomas and oligodendrogliomas, correlate with better prognosis, longer survival, and increased treatment response, particularly to temozolomide." (PMID 40507765, 2025). "Studies revealed that IDH1 mutations occur in approximately 80-90% of LGGs, including astrocytomas and oligodendrogliomas." (PMID 40661781, 2025). "IDH1 mutant malignant astrocytomas are more amenable to surgical resection, and IDH1 mutation is associated with improved resection rates, progression-free survival, and overall survival." (PMID 40134593, 2025). "We saw that the REMBRANDT diagnosis was more weighted in oligodendroglioma and astrocytomas, both diseases that are known to harbor IDH1 mutations." (PMID 39941811, 2025). "It was approved by the FDA in August 2024 for patients aged 12 and over with grade 2 astrocytomas or oligodendrogliomas with IDH1 or IDH2 mutation post-surgery." (PMID 40862786, 2025). "It is known that IDH1/2 mutations are ubiquitous in IDH-mutant astrocytomas, which means that all tumor cells present a heterozygous mutation of IDH1 or IDH2 and retain a wild-type allele, necessary for tumor cell survival." (PMID 41373636, 2025). "In contrast, grade 4 IDH-mut astrocytomas are classified using updated grading systems emphasizing alterations such IDH1/2 mutations and ATRX loss." (PMID 40722659, 2025). "CDKN2A/B homozygous-loss associates with worse survival in IDH1/2-mutant astrocytomas (IDHmut-astrocytomas), the presence of which denotes a grade 4 tumor independent of histologic features." (PMID 39584448, 2025). "IDH1/2 mutations were correctly identified in 3 of 3 oligodendrogliomas and 6 of 7 astrocytomas; in one case, low tumor DNA fraction impaired analysis." (PMID 40392954, 2025). "According to the updated WHO 2021 classification, three patients would now be categorized as grade 4 astrocytomas due to the presence of an IDH1 mutation." (PMID 39941744, 2025). "The dual inhibitor of mutant IDH1/2 enzymes, vorasidenib, received approval in the USA for the treatment of low-grade astrocytoma or oligodendroglioma with IDH1/2 mutations in 2024." (PMID 40469416, 2025). "On univariate analysis, IDH1/2-mutant astrocytoma patients with CDKN2A/B hemizygous loss exhibited significantly shorter survival than their intact CDKN2A/B counterparts within each grade." (PMID 39584448, 2025). "Age also showed associations with molecular alterations in IDH1/2-mutant astrocytomas and oligodendrogliomas, where patients <40 years old exhibited distinct correlated molecular alterations compared to those between 40 and 64 and ≥65 years." (PMID 39164213, 2025). "They reported IDH1 mutation as being also associated with oligodendrogliomas and astrocytomas (p = 0.005) and being more frequent in males (p = 0.0002) but not significant among age groups." (PMID 39767640, 2024). "As such, tumors with IDH1/2 mutations designated a diagnosis of either IDH-mutant astrocytoma or IDH-mutant secondary glioblastoma multiforme, depending on the morphologic characteristics of the tumor." (PMID 38893099, 2024).